MIR3973 (microRNA 3973)
Synonyms: hsa-mir-3973
Gene: MicroRNA gene on chromosome 11 (36,010,098 to 36,010,204, forward strand). Ensembl gene ENSG00000263389.
Homologues: Orthologues: chimpanzee MIR3973 (100% identical).